IL6 (interleukin 6)
Diseases named in the same sentence as IL6 in open-access papers (continued):
Sharing a sentence is not in itself a finding about the gene and the disease.
depression (continued). "The study identified the IL6 rs2069827 polymorphism as having a statistically significant association with symptoms of depression." (PMID 41009999, 2025). "In group I, IL-6 exhibited a positive and moderately strong association with the Hamilton depression scale (r = 0.433, p < 0.05) and the Beck depression scale (r = 0.417, p < 0.05)." (PMID 40699818, 2025). "IL‐6 influences the risk of depression through two distinct signaling pathways: classical IL‐6 signaling and trans IL‐6 signaling." (PMID 39888279, 2025). "We examined the associations between serum IL-6 levels at baseline and subsequent depression symptom trajectories in two longitudinal cohorts: ALSPAC (age 10–28 years; N = 4,835) and UK Biobank (39–86 years; N = 39,613) using multilevel growth curve modeling." (PMID 39865800, 2025). "Specifically, lower difficulties in positive emotion regulation were associated with higher CRP and IL-6 levels correlated with decreased depression scores and reduced stress responses, respectively." (PMID 41333345, 2025). "A decrease in IL-6 levels was observed in the bolus group, while daily vitamin D supplementation was associated with improvements in anxiety and depression scores." (PMID 40429727, 2025). "Sedentarism-related inflammatory responses, such as increased interleukin-6 and decreased brain-derived nerve growth factor levels, are recognized as pathological causes of emotional stress and depression." (PMID 40508900, 2025). "Studies have also shown that exercise reduces levels of pro-inflammatory factors (e.g., TNF-α and IL-6), which are strongly associated with suicidal tendencies and depression." (PMID 40584058, 2025). "The purpose of this study was to examine associations between cytokines TNF-α, IL-1β, IL-6, and IL-8 and depression among a community-based sample of adolescents (13–19 years of age)." (PMID 39902492, 2025). "Markers of inflammation or immune activation (including TNFα, CRP, IL-6) are closely associated with depression and sleep quality." (PMID 40313235, 2025). "Research has shown that the excessive activation of pro-inflammatory cytokines, such as IL-1β, TNF-α, and IL-6, is closely associated with the pathogenesis of many central nervous system disorders, including depression." (PMID 40336842, 2025). "In this study, the daily regimen was associated with reductions in anxiety and depression symptoms, whereas the bolus regimen was associated with a greater reduction in IL-6 levels." (PMID 40429727, 2025). "The elevated IL-6 levels verify the existence of neuroinflammation linked to depressive states in the depression control group." (PMID 40574754, 2025). "A meta-analysis showed that higher concentrations of TNF-α, IFN-γ, IL-6 and IL-10 were significantly associated with higher levels of depression in individuals with MS (r = 0.35, 95% CI [0.6,0.03], p = .015." (PMID 39867847, 2025). "Elevated levels of TNF-α and IL-6 have also been linked to depression, as they exacerbate and perpetuate neuroinflammatory processes, impairing brain function." (PMID 40141696, 2025). "Studies have shown that an increased IL-6 concentration in the peripheral blood is associated with cognitive dysfunction, depression, and fatigue in the acute stage of stroke." (PMID 40709232, 2025). "This includes prospective and genetic evidence linking elevated inflammatory signaling to depression risk (e.g., childhood IL-6/CRP predicting adult depression; IL-6 pathway Mendelian randomization), and associations with aggression-related psychopathology." (PMID 41008344, 2025). "Higher CRP levels frequently precede the onset of depression in population studies, and Mendelian randomization suggests causal links between IL-6, CRP, and depression." (PMID 41333345, 2025). "Depression was associated with decreased IL6 methylation compared to controls, while antidepressant usage, particularly SSRI-class drugs, was associated with an increase in IL6." (PMID 39940850, 2025).
depression (continued). "Materials and Methods: In our study, we explored the association between TNF-α and IL-6, disease activity, and the degree of depression in patients with RA." (PMID 40699818, 2025). "Conversely, in males, inflammation was inversely associated with depression severity, with protective effects from regulatory mediators (IL-2, IL-4, IL-6, IL-15, LIF, TNF-α, β-NGF) against depression." (PMID 40305313, 2025). "IL-6 was thought to be a associated factor for many neuropsychiatric diseases, such as Alzheimer's disease, and depressive disorder." (PMID 40746414, 2025). "IL-6 has also been linked to specific symptoms or subtypes of depressive disorder such as reduced appetite, sleep disturbances, low mood, and feelings of worthlessness." (PMID 39867847, 2025). "Stress triggers BBB disruption, allowing IL-6 to penetrate the brain and increases the risk of depression in humans." (PMID 38898454, 2024). "Increased levels of the pro-inflammatory cytokine IL-6 can increase the activity of brain regions implicated in the etiology of depression and impair brain connectivity causing mood reduction." (PMID 38645426, 2024). "According to the literature, both IL-6 and IL-8, using various measurement tools, showed significant associations with QoL categories including pain, depression, and fatigue." (PMID 38744744, 2024). "CRP and IL-6 levels are not only associated with cognitive symptoms of depression at baseline but also predicted those symptoms at a 12-year follow-up." (PMID 39565757, 2024). "A novel multi-protein-derived measure of IL-6 activity/bioavailability shows robust associations with various inflammation-related clinical and cognitive outcomes in depression and performs well in comparison to single inflammatory proteins." (PMID 38442505, 2024). "Meanwhile, there is a positive association between frailty and levels of inflammatory cytokines, which are associated with depression and sleep quality, including interleukin 6 (IL-6)." (PMID 38645453, 2024). "IL-6 together with the FMI also mediated the association between depression and any respiratory symptoms, and the total proportion of mediation was 20.3%." (PMID 39523673, 2024). "Inflammatory cytokines like interleukin-6 (IL-6) are implicated in depression, but most studies have hitherto focused on circulating levels of IL-6 rather than its activity." (PMID 38442505, 2024). "The depletion of peripheral tryptophan, the precursor to serotonin (5-HT), has been linked to IL-6-induced short-term mood alterations resembling depression, according to studies." (PMID 38670978, 2024). "There is an association between ACEs, depression, and elevated levels of interleukin-6 (IL-6), as well as an association between high levels of C-reactive protein in depressed elderly individuals and ACEs in childhood." (PMID 39335507, 2024). "Despite the paucity of immunological markers during episodes of depression with psychotic features elevated levels of IL-6 during childhood and adolescence have been associated with an increased risk of developing depression and psychosis in early adulthood." (PMID 39355377, 2024). "As numerous research studies outlined the associations between depression and IL-6, we measured the expression and release of IL-6 in LPS-treated BV2 microglial cells." (PMID 38674048, 2024). "The results revealed significant changes in IFN-γ and IL-6 levels within the test group, indicating that the soothing Liver-Qi stagnation method effectively mitigates inflammatory factors associated with depression." (PMID 39287310, 2024). "The effect estimates for the associations of the novel measure with depression outcomes were comparable to those for individual immune proteins (i.e., IL-6, CRP, sIL-6R)." (PMID 38442505, 2024). "One study found that cytokines and tryptophan metabolites predicted depression during pregnancy and that IL-1β and IL-6 levels were associated with severity of depression symptoms during pregnancy and postpartum." (PMID 38820411, 2024).
depression (continued). "Excessive IL-6 can also cause depression, presumably via activating the hypothalamic-pituitary-adrenal axis or via altering the neurotransmitter metabolism." (PMID 38646100, 2024). "Inflammatory factors released from adipose tissue, such as tumour necrosis factor-a (TNF-a) and interleukin-6 (IL-6), can travel through the bloodstream to the brain and cause depression." (PMID 39346588, 2024). "5-HIAA levels are significantly associated with depression and anxiety scores in patients with somatic symptom disorder, and elevated IL-6 levels exhibit mediating effects." (PMID 38898454, 2024). "We tested the association between a multi-protein-derived measure of IL-6 trans-signalling and clinical and cognitive outcomes in patients with depression." (PMID 38442505, 2024). "Brown first reported that individuals who had a high IL-6 concentration in blood (3.2 pg/mL) together with previous slow gait and depression, were associated with slow gait." (PMID 38338653, 2024). "IL-6 was assessed in 10 of the 14 studies that explored the association between depression and inflammatory biomarkers during pregnancy, but only in two was found a significant positive association." (PMID 38820411, 2024). "Lipocalin-2 (LCN2), a pro-inflammatory cytokine mediator, has been associated with depression and is often accompanied by elevated levels of IL-6 and TNF-α." (PMID 39273621, 2024). "Treatment-resistant depression patients are characterized by elevated inflammatory proteins, with increased interleukin 6 and 8 linked to poorer treatment outcomes." (PMID 39415236, 2024). "In contrast, MR studies have shown more consistent findings for the potential causal role of IL-6 on depression." (PMID 38699368, 2024). "Elevated inflammatory factors, such as TNF-α and IL-6, are strongly associated with the development of depression." (PMID 39479195, 2024). "We add to this evidence base, showing associations between a marker of IL-6 activity/bioavailability and somatic symptoms, fatigue, and depression severity." (PMID 38442505, 2024). "In an epidemiological study of HNC patients, IL-6 was observed to be a key marker linked with diurnal salivary cortisol aberrations and anxiety, depression, poor sleep quality, fatigue, and reduced quality of life." (PMID 39634268, 2024). "Patients with depression exhibit similar changes associated with immune system activation, such as increased IL-6, TNF-α, and C-reactive protein levels." (PMID 38702637, 2024). "In this study, we aimed to more precisely assess the association between inflammation and depression by measuring inflammatory markers (IL-6, IL-1α, and TNF-α)." (PMID 39595067, 2024). "The XJ strain’s significant induction of IL-1β and IL-6 in the brain implies a propensity for causing severe neurological damage, aligning with observed clinical symptoms like muscle spasms and depression." (PMID 39170631, 2024). "Our study also showed that zileuton reduced hippocampal inflammation, as evidenced by the significant reduction in the IL-6 level, a pro-inflammatory cytokine implicated in depression." (PMID 39624549, 2024). "Six hours after the administration of the various treatments, the elevation in IL-6 was associated with depression-like behavior, reflected by staying in a corner of the cage for the whole 5 min of observation." (PMID 39451220, 2024). "Ho, Teresi reported that levels of IL-6 are associated with neuroinflammation in young adolescents with depression while Vints, Kušleikiene found a significant relationship between elevated levels of serum kynurenine and neuroinflammation in older adults." (PMID 38297218, 2024). "The immune system and MDD are closely related, allowing for the use of certain cytokines as a diagnostic biomarker such as IL-6, which is increased in patients with treatment-resistant major depression." (PMID 38541952, 2024).
depression (continued). "It is important to remember that the “cytokine theory of depression” proposes that enhanced production of proinflammatory cytokines (such as IL-6, IL-1β, IFN-γ, and TNFα) is associated with the pathogenesis of depression." (PMID 38731995, 2024). "Secondly, a compelling association emerges between depression and an augmented inflammatory response, underscored by elevated levels of inflammatory mediators, notably cytokines like interleukin-6 and tumor necrosis factor-alpha, in affected individuals." (PMID 38805405, 2024). "A meta-analysis showed that high levels of CRP and IL-6 are associated with future depressive symptoms, suggesting that inflammatory cytokines are potentially important biological markers in depression research." (PMID 38377025, 2024). "Studies have shown that depression is often accompanied by elevated levels of pro-inflammatory markers such as C-reactive protein and interleukin-6, which not only lead to the onset and progression of depression but also significantly increase the risk of CVD." (PMID 39450305, 2024). "These authors found that coronary heart disease and depression shared multiple risk factors, including elevations in triglycerides and inflammatory markers, including interleukin 6 (IL-6) and CRP." (PMID 38505265, 2024). "Both animal models and clinical studies demonstrate an increased inflammatory milieu associated with depression, including increased levels of interleukin-1beta (IL-1b), IL-6, tumor necrosis factor-alpha (TNFa), and interferon-gamma (IFN-g)." (PMID 39297528, 2024). "One key indicator of this influence is an elevated concentration of interleukin-6 in patients after surgery—this pro-inflammatory cytokine is linked to heart disease and psychiatric disorders, including depression." (PMID 39403242, 2024). "Given that iMCD is an inflammatory cancer characterized by increased serum IL-6 levels, our results are compatible with prior studies and implicated inflammation in the pathophysiology of depression in iMCD." (PMID 39702341, 2024). "In those suffering from rheumatoid arthritis, a condition where depression-related symptoms are linked to high IL-6 levels, treatment with sirukumab significantly improved the reduction of depressive symptoms by the eighth week." (PMID 39273641, 2024). "High serotonin levels are linked to the activation of inflammatory mediators, including interleukin‐6 (IL‐6), which has been suggested to cause depression through modulation of the HPA axis." (PMID 39225086, 2024). "A large population-based prospective cohort study shows that childhood IL-6 levels are associated with depression risk in early-adulthood in a dose-response fashion." (PMID 38442505, 2024). "Another small study of 47 MS patients found that IL-6 in CSF was independently associated with depression and fatigue." (PMID 38304427, 2024). "A proposed mechanism for elucidating how poor sleep quality increases depression risk is an increase in the expression of inflammatory markers, such as C-reactive protein and interleukin-6 (IL-6)." (PMID 39850107, 2024). "Secondary outcomes include assessing the impact of these supplementations on additional markers such as plasma levels of inflammation markers CRP and IL-6, cardiovascular risk factors, and depression." (PMID 39139799, 2024). "Pro-inflammatory cytokines such as tumor necrosis factor-alpha (TNF-α), interleukin 6 (IL-6), and interleukin 1 beta (IL-1β) are elevated in psoriasis and have been implicated in the pathophysiology of depression and anxiety." (PMID 39335361, 2024). "Proinflammatory cytokines such as interleukin 1 (IL-1) and interleukin 6 (IL-6) have been implicated in both pSS and depression." (PMID 38774059, 2024). "Depression is known to be associated with neuroinflammation and with increased levels of C-reactive protein, interleukin-6 (IL-6) and tumor necrosis factor (TNF)-α." (PMID 39064764, 2024).
depression (continued). "IL-6 has been associated with the pathophysiology of depressive disorders as well as with prognosis and therapeutic response to antidepressants." (PMID 35796659, 2024). "Since the early 1990s, studies have associated depressive disorders with altered levels of circulating inflammatory markers, such as interleukin (IL)-6 and tumor necrosis factor (TNF)." (PMID 35796659, 2024). "Patients with ENS with severe depression had higher serum IL-6 levels than the rest of the population, and those with preoperative IL-6 levels > 1.985 pg/mL had a nearly 10-fold risk of experiencing severe depression." (PMID 37324195, 2023). "IL-6 activation has been linked to the induction of various inflammatory mediators, including nitric oxide (NO), which is well established in depression." (PMID 37754268, 2023). "There is, however, evidence from genetic research that inflammation (increased interleukin 6 activity) is a risk factor for anxiety/depression and suicidality, and higher polygenic risk scores for depression in those with psoriasis, and vice versa." (PMID 37542272, 2023). "The study of injecting lipopolysaccharide into healthy volunteers showed that serum IL-6 increased in the peripheral immune system, and symptoms such as depression, anxiety and cognitive decline were caused." (PMID 36984504, 2023). "Aruldass and colleagues (2021) recently showed that IL-6 was associated with lower functional connectivity between regions of the default mode network in a sample of patients with major depressive disorder, using resting state fMRI (N = 83)." (PMID 37339948, 2023). "It is also reported that the −174G/C polymorphism IL6 in interaction with various stress factors increases the risk of depression and has a greater impact on symptoms measured by the Zung Self-rating Depression Scale." (PMID 37510364, 2023). "In the current naturalistic study, among the veterans at highest risk with current depression and history of suicide attempt, decreases in levels of suicidal ideation were significantly associated with decreases in IL-6 levels over 6 months of observation." (PMID 37779624, 2023). "Anxiety or depression causes an increased level of Interleukin-6 in serum, which can enhance the immune response to vaccine and induce adverse reactions." (PMID 36869301, 2023). "In our cohort of women with elevated depression and anxiety, specific pro-inflammatory cytokines, i.e., IL-6 and CRP, were positively associated with more elevated scores of depression and/or anxiety." (PMID 37107316, 2023). "Higher levels of depression symptoms were associated with increased levels of pro-inflammatory biomarker IL-6 in caregivers caring for an older person in the community." (PMID 37637801, 2023). "Multiple studies have implicated increased peripheral and central IL-6 levels in a wide spectrum of psychiatric disorders, such as major depression, schizophrenia, and autism." (PMID 37187893, 2023). "A recent study showed that higher interleukin 6 activity is potentially causal especially for specific symptoms of depression, such as sleep problems or fatigue." (PMID 37390107, 2023). "IL-6 wasindependently associated with depression; however, anxiety was associated with IL-33and CRP levels." (PMID 37712803, 2023). "According to Lee STH, IL-6 is associated with depression as a predictive factor, on average 6 years prior to its onset, and is positively correlated with its increase, as well as the presence of anxiety symptoms." (PMID 37693246, 2023). "The increase of CRP and IL-6 in different age groups is related to the increased risk of depression, and the increased level of IL-6 in childhood is related to the occurrence of depression in adulthood." (PMID 36846218, 2023). "IL-6 levels play a pivotal role in the relationship between inflammatory disorders, depression, and anxiety, where low levels of IL-6 are associated with anxiety and high levels are associated with depression." (PMID 37346903, 2023).